APLNR (apelin receptor)
Diseases named in the same sentence as APLNR in open-access papers (continued):
Sharing a sentence is not in itself a finding about the gene and the disease.
glioblastoma (13 papers, 2016 to 2025). The most malignant astrocytic tumor (WHO grade IV). "The neurovascular peptide Apelin and its receptor APLNR are upregulated during glioblastoma pathology." (PMID 34359800, 2021). "Analysis of APELA and the Apelin receptor gene expression in brain tumor datasets showed that high APELA expression was associated with poor patient survival in both glioma and glioblastoma, and APELA expression correlated with glioma grade." (PMID 30917521, 2019). "To explore the APLNR downstream signalling further, we interrogated the TCGA database for reverse phase protein array (RPPA) in glioblastoma patients with high and low APLNR expression." (PMID 29053791, 2017). "Collectively, these in vivo data provide a strong basis for the clinical potential of apelin/APLNR signalling as a therapeutic target in glioblastoma." (PMID 29053791, 2017). "Our therapeutic hypothesis is that the apelin receptor contributes to the development and progression of glioblastoma, and supported by results from animal models, apelin antagonist may act in combination with current standard-of-care to improve the treatment of this condition." (PMID 38803685, 2024). "Pharmacological targeting of APLNR impaired the growth of glioblastoma cells in vitro and in GBM xenografts in vivo." (PMID 30917521, 2019). "In glioblastoma cells, upregulation of both the APLN and the Apelin receptor (APLNR) allow control over the invasiveness of tumor cells take place." (PMID 38804848, 2024). "The results demonstrated that APLN and APLNR mRNA expression were significantly increased in CNS cancers, including both low-grade glioma (LGG) and glioblastoma (GBM), when compared with normal CNS tissues." (PMID 36193059, 2022). "Therefore, the apelin/apelin receptor signalling nexus may operate as a paracrine signal that sustains tumour cell expansion and progression, suggesting that apelin is a druggable factor in glioblastoma." (PMID 29053791, 2017).
Stroke (12 papers, 2015 to 2024). Sudden impairment of blood flow to a part of the brain due to occlusion or rupture of an artery to the brain. "In a previous genome-wide association study, a functional variant (rs9943582, –154G/A) in the 5’ flanking region of the apelin receptor gene (APLNR) was shown to be significantly associated with stroke in the Japanese population." (PMID 29296197, 2017). "Noteworthy, genetic APLNR variants have been associated with the increased stroke risk in humans." (PMID 33344448, 2020). "In addition, the apelinergic system, comprising apelin and APLNR, is important in recovery after stroke by inhibiting neuronal apoptosis and promoting angiogenesis through various molecular pathways." (PMID 37965346, 2023).
cardiac hypertrophy (11 papers, 2015 to 2024). "It has been proposed that the apelin‐induced cardioprotective effect is primarily attributed to Gi signalling of APLNR, whereas the β‐arrestin pathway of APLNR causes detrimental cardiac hypertrophy." (PMID 39648165, 2024). "We recently reported that miR-204 promotes APJ (apelin-receptor) endocytosis via a dynamin-independent, calcium-dependent mechanism and confers protection against cardiac hypertrophy and dysfunction." (PMID 36010634, 2022). "A recent study on APLNR knockout mice showed that APJ receptor could induce a pathological stretch signaling pathway and triggered myocardial hypertrophy under the condition of pressure overloading." (PMID 25993436, 2015).
ischemic stroke (11 papers, 2014 to 2023). A stroke disorder caused by obstruction of blood flow to the brain, due to thrombotic (local blood clot formation) or embolic (due to a blood clot or other material traveling from another site) event. "The association between other polymorphisms in the APLNR genomic region and ischemic stroke requires additional study." (PMID 29296197, 2017). "Apelin receptor AGTRL1 was shown to associate with the development of ischemic stroke in the most recent genome-wide association study for ischemic stroke." (PMID 26391329, 2015). "One limitation of the present study is that only one variant (rs9943582) was selected to investigate the genetic association between APLNR and ischemic stroke risk; therefore, our study cannot exclude the possibility that other APLNR variants confer risk to ischemic stroke." (PMID 29296197, 2017). "To validate the genetic relationship between the APLNR variant and ischemic stroke in the Chinese Han population, we evaluated the contribution of rs9943582 to the genetic susceptibility of ischemic stroke in the Chinese GeneID population including 1,158 ischemic stroke patients and 1,265 controls." (PMID 29296197, 2017). "Large-scale genome-wide association studies (GWAS) have identified loci conferring risk to ischemic stroke, including variants in 11q12.1 (APLNR), 12p13 (NINJ2), 12q24 (ALDH2), 7p21 (HDAC9), 9p21 (ANRIL), 4q25 (PITX2), 16q22 (ZFHX3), 9q34 (ABO), and 1p13.2 (TSPAN2)." (PMID 29296197, 2017). "The later-stage reduction of apelin and APLNR may be associated with a plethora of mechanisms in ischemic stroke." (PMID 28167898, 2017). "Therefore, the temporal expression of apelin/APLNR in ischemic stroke and the underlying mechanisms need to be further investigated, which is crucial for the therapeutic application of apelin or APLNR agonists to treat ischemic stroke." (PMID 28167898, 2017). "Blocking this vicious cycle by suppressing oxidative stress is a major mechanism of apelin/APLNR’s protective effects on ischemic stroke." (PMID 28167898, 2017). "Accumulated evidence indicates that the apelinergic system, consisting of apelin and apelin receptor (APLNR), is temporally dysregulated in ischemic stroke." (PMID 28167898, 2017). "A growing body of evidence indicates that the apelinergic system, consisting of apelin and apelin receptor (APLNR), is implicated in ischemic stroke." (PMID 28167898, 2017). "In this review article, we summarize the temporal expression of apelin and APLNR in ischemic stroke and the mechanisms of their dysregulation." (PMID 28167898, 2017). "Thus, a comprehensive, mechanistic understanding of the role of APLNR and its dynamic patterns of expression during ischemic stroke are necessary before testing potential therapeutic applications of APLNR agonists in a clinical setting." (PMID 37965346, 2023). "Recent studies indicate that the expression of apelin and APLNR may be temporally regulated in ischemic stroke." (PMID 28167898, 2017). "To validate the genetic relationship between APLNR and ischemic stroke in the Chinese Han population, we genotyped rs9943582 in a case–control population containing 1,158 ischemic stroke patients and 1,265 common controls enrolled from the GeneID database, and performed a genetic association study." (PMID 29296197, 2017). "Therefore, we summarize the temporal expression of apelin and APLNR in ischemic stroke, the mechanisms of their dysregulation, the protective effect of the apelinergic system on ischemic stroke and the underlying mechanisms of its protective effect." (PMID 28167898, 2017). "Moreover, the expression of apelin and APLNR is temporally dysregulated during different phases of ischemic stroke." (PMID 28167898, 2017). "In addition, PI3K/AKT and ERKs signaling pathways play a crucial role in apelin/APLNR-induced angiogenesis in ischemic stroke, which may be mediated by VEGF-VEGFR2." (PMID 28167898, 2017).
myocardial infarction (11 papers, 2014 to 2025). Gross necrosis of the myocardium, as a result of interruption of the blood supply to the area, as in coronary thrombosis. "Myocardial infarction resulted in an increase in apelin and apelin receptor expression by about 2-fold." (PMID 36986889, 2023). "Myocardial infarct could affect apelin and apelin receptor expression in the heart." (PMID 36986889, 2023). "Additionally, we found that APLNR inhibition reduced myocardial infarction." (PMID 37942483, 2023).
ovarian carcinoma (11 papers, 2020 to 2025). A malignant neoplasm originating from the surface ovarian epithelium. "The result was in line with the previous reports that APLN/APLNR gene expression were increased in gastric cancer, liver cancer, cholangiocarcinoma, lung cancer, ovarian cancer, prostate cancer, etc., compared with the equivalent normal tissues or cells." (PMID 36193059, 2022). "APLN/APLNR mRNA and protein expression in ovarian epithelial cancer and/or granulosa tumor cell lines were significantly higher than those of noncancer ovarian cell lines." (PMID 36193059, 2022). "Apelin suppresses the proliferative effect of estrogen on epithelial (OVCAR-3) ovarian cancer cell lines and insulin-like growth factor 1 (IGF-1) on granulocyte (COV434) ovarian cancer cell lines by the interaction of the apelin receptor with those hormones’ receptors." (PMID 40076482, 2025). "In addition, a meta-analysis of 16 ovarian cancer cell lines and ovarian tumors suggested a significantly elevated APLNR expression that is correlated with poor prognosis in patients with serous ovarian cancer." (PMID 35052372, 2021). "In support of our findings, several ovarian cancer cell lines such as OVCAR-3, -4, -5 and SKOV3 and high grade serous ovarian carcinoma (HGSOC) tissue were found to have greater expression of mRNA and protein of APLNR and its ligand apelin as compared to normal ovarian surface epithelium." (PMID 35052372, 2021).
preeclampsia (11 papers, 2018 to 2025). Preeclampsia is a hypertensive disorder of pregnancy that is characterized by new-onset hypertension with proteinuria presenting after 20 weeks of gestation, and depending on mild or severe forms may initially present with severe headache, visual disturbances, and hyperreflexia. "The apelin receptor system is a pleiotropic pathway with a potential for therapeutic targeting in preeclampsia." (PMID 31189936, 2019). "The genetic deletion of apelin receptor early endogenous ligand (Elabela; official name APELA) produces a preeclampsia-like phenotype in mice." (PMID 29803833, 2018).
colon carcinoma (9 papers, 2017 to 2025). "Given the co-expression of apelin, apelin receptor and Furin, that we identified in colon tissues, colon carcinoma cells, and endothelial cells, we sought to evaluate their expression and colocalization in both normal and colon cancer tissues." (PMID 39962271, 2025). "Taken together, these findings indicate that the increased co-expression levels of apelin, the apelin receptor, and/or Furin are associated with CRC tumors, suggesting a potential role for these proteins in colon cancer progression and metastasis." (PMID 39962271, 2025). "Furthermore, APLNR and Furin were overexpressed in metastatic tumors, with levels higher than those in matched healthy and primary colon tumors." (PMID 39962271, 2025). "Indeed, all the analyzed colon cancer cells express both apelin and the apelin receptor." (PMID 39962271, 2025). "We next explored the correlation between the expression of APLN and APLNR with genes that are dysregulated by APLN or APLN-DM expression in cancer cells, and involved in prognosis of colon cancer patients." (PMID 39962271, 2025). "Overall, we present apelin-dm as a potent, selective, non-toxic inhibitor of the apelin receptor interaction, demonstrating efficacy in a mouse model of colon cancer and colorectal liver metastasis." (PMID 39962271, 2025).
ischemia (9 papers, 2015 to 2025). A hypoperfusion of the BLOOD through an organ or tissue caused by a PATHOLOGIC CONSTRICTION or obstruction of its BLOOD VESSELS, or an absence of BLOOD CIRCULATION. "We found that APLNR was induced in the renal tubular cells of the ischemia-induced AKI model, whereas initial/prior apelin-13 administration affected tubular proliferation after renal I/R." (PMID 40177358, 2025). "The lack of protective effects of apelin-13 is in agreement with our findings, suggesting that the apelin/APLNR signaling pathway may be either disrupted or insufficient to counteract the deleterious effects of ischemia-induced AKI." (PMID 40177358, 2025). "The apelinergic system is composed of the apelin receptor (APJ) with two endogenous peptide ligands/hormones: apelin and the newly discovered Elabela (ELA, Apela or Toddler) and is emerging as a protective system against tissue damage in ischemia and inflammation." (PMID 32808659, 2020).
coronary artery disease (8 papers, 2012 to 2025). "In this meta-analysis, we summarized published results on circulating apelin concentration in association with coronary artery disease (CAD), apelin and APLNR genetic polymorphism(s) in predisposition to CAD risk and circulating apelin changes after surgical treatment for CAD." (PMID 28915675, 2017).
type 2 diabetes (8 papers, 2012 to 2025). "The relative amount of APLNR mRNA in the kidneys of type 2 diabetic mice (KK mice) was increased 5.2-fold compared to the relative mRNA amount in the kidneys of control mice (C57BL/6) (n = 3, p<0.01 vs. control group)." (PMID 23577111, 2013). "Therefore, we observed apelin/APLNR expression in kidneys from patients with type 2 diabetes as well as the correlation between albuminuria and serum apelin in patients with type 2 diabetes." (PMID 23577111, 2013). "In addition, we detected apelin and APLNR expression in the kidneys of type 2 diabetic mice (KK mice)." (PMID 23577111, 2013). "For instance, APLNR, encoding apelin APJ system is implicated in psychosis and neuropathy processes in chronic schizophrenia but also acts as a promising biomarker for the treatment of type 2 diabetes given its functions in energy metabolism in insulin resistance progress via adipokines involvement." (PMID 38573526, 2024).
colorectal cancer (7 papers, 2014 to 2025). A primary or metastatic malignant neoplasm that affects the colon or rectum. "Furthermore, Studies demonstrate that APLNR serves as an angiogenesis indicator in colorectal cancer and reduces tumor angiogenesis in lung and breast cancer.Which positioning APLNR as a potential target for anti-tumor vascular therapy." (PMID 41316451, 2025). "Therefore, the upregulation of the apelin receptor during colorectal cancer progression is possible to detect in patients’ serum." (PMID 31547096, 2019). "In this study, we examined apelin and apelin receptor expression level in colorectal cancer." (PMID 31547096, 2019).
Insulin resistance (7 papers, 2011 to 2025). Increased resistance towards insulin, that is, diminished effectiveness of insulin in reducing blood glucose levels. "Insulin resistance can impair signaling pathways that regulate APLNR expression and leptin secretion." (PMID 41302116, 2025). "These factors can lead to the observed decrease in apelin receptor mRNA expression and leptin concentration, which may predict the outcome of insulin resistance and poor glucose metabolism before the manifestation of GDM." (PMID 41302116, 2025). "Insulin resistance may impair signaling pathways that regulate apelin receptor expression and leptin secretion." (PMID 41302116, 2025).
chronic heart failure (6 papers, 2018 to 2024). "Developing antibody agonists targeting the human apelin receptor (APJ) is a promising therapeutic approach for treating chronic heart failure." (PMID 39359422, 2024). "Clinical trials of apelin receptor agonism are now needed in both acute and chronic heart failure." (PMID 37956047, 2023).
depression (6 papers, 2017 to 2025). "The goal of this study was to investigate the association between APLN/APLNR gene polymorphisms and the risk of depression and anxiety in CHD patients." (PMID 32849850, 2020). "This is the first pharmacogenomics study to examine the associations between polymorphisms located in genes of the APLN/APLNR pathway and the susceptibility to depression and anxiety in patients with CHD." (PMID 32849850, 2020). "We further investigated the influence of APLN/APLNR pathway polymorphisms on the risks of depression and anxiety in patients with CHD." (PMID 32849850, 2020). "In this study, we investigated the associations of four promising polymorphisms in the APLN/APLNR pathway with the risks of depression and anxiety in patients with CHD." (PMID 32849850, 2020). "The present study supports the hypothesis that APLN/APLNR polymorphisms contribute to the susceptibility to depression and anxiety in Chinese patients with CHD." (PMID 32849850, 2020). "Our principal findings demonstrated that genetic polymorphisms in the APLN/APLNR pathway might result in a potential risk for depression and anxiety in patients with CHD." (PMID 32849850, 2020). "Therefore, the present study aimed to evaluate the association between APLN and APLNR gene polymorphisms and the risk of comorbid depression and anxiety in Chinese patients with CHD." (PMID 32849850, 2020). "The apelin receptor (APLNR) rs9943582 polymorphism has been implicated in increased CAD risk, and its C allele has been linked to both depression prevalence and severity in patients with CHD." (PMID 41301929, 2025). "The apelin receptor (APJ) is a member of the family A of G-protein-coupled receptors (GPCRs) and is involved in range of physiological and pathological functions, including fluid homeostasis, anxiety, and depression, as well as cardiovascular and metabolic disorders." (PMID 33679444, 2021). "The Apelin (APLN)/apelin receptor (APLNR) signaling pathway is a newly identified regulator in various cardiovascular diseases, which is considered as a candidate pathway for the occurrence of coronary heart disease (CHD), depression, and anxiety." (PMID 32849850, 2020). "Thus, the APLN/APLNR signaling pathway is considered a candidate pathway for the occurrence of CHD, depression, and anxiety." (PMID 32849850, 2020).
hepatocellular carcinoma (6 papers, 2016 to 2025). A malignant tumor that arises from hepatocytes. "The apelin receptor (APJ) is a key player in tumour angiogenesis, but its role in hepatocellular carcinoma (HCC) remains unclear." (PMID 39434201, 2024).
lung carcinoma (6 papers, 2021 to 2025). "Recently, APLN/APLNR was shown to be involved in several kinds of cancers, such as lung cancer, gastroesophageal cancer, colonic cancer, and hepatocellular carcinoma." (PMID 36193059, 2022). "For example, expression of the G protein-coupled receptor family member apelin receptor (APLNR) has been shown to promote proliferation and cell autophagy via ERK1/2 signaling in human lung cancer cells." (PMID 34870316, 2022).